RN7SKP180 (RN7SK pseudogene 180)
Gene: Miscellaneous RNA gene on chromosome 17 (72,663,823 to 72,664,152, reverse strand). Ensembl gene ENSG00000200783.
Homologues: Orthologues: chimpanzee 7SK (92% identical), mouse Gm54658 (70% identical). Paralogues in human: 7SK (77% identical), RN7SKP203 (76% identical), RN7SKP9 (75% identical), RN7SKP176 (75% identical), RN7SKP255 (75% identical), RN7SKP90 (75% identical), RN7SKP170 (74% identical), RN7SKP79 (74% identical), RN7SKP189 (73% identical), RN7SKP133 (73% identical), RN7SKP118 (73% identical), RN7SKP124 (73% identical), and 284 more.